Y_RNA (Y RNA )
Gene: Miscellaneous RNA gene on chromosome 15 (32,175,247 to 32,175,351, reverse strand). Ensembl gene ENSG00000201084.
Homologues: Orthologues: chimpanzee Y_RNA (98% identical), macaque Y_RNA (97% identical). Paralogues in human: Y_RNA (100% identical), Y_RNA (85% identical), RNY3 (84% identical), Y_RNA (84% identical), RNY3P1 (83% identical), Y_RNA (83% identical), Y_RNA (82% identical), Y_RNA (81% identical), Y_RNA (80% identical), RNY3P11 (79% identical), RNY3P16 (79% identical), Y_RNA (79% identical), and 93 more.